G6PD (glucose-6-phosphate dehydrogenase)
Diseases named in the same sentence as G6PD in open-access papers (continued):
Sharing a sentence is not in itself a finding about the gene and the disease.
breast cancer (continued). "More in detail, by using MCF-7 and MDA-MB-231 breast cancer cells, the authors showed that the inhibition of NRF2 and overexpression of Kelch-like ECH-associated protein-1 (KEAP1) reduced the expression of G6PD, while NRF2 overexpression or KEAP1 knockdown had the opposite effect." (PMID 33805996, 2021). "However, the expression of G6PD and GART, enzymes associated with the PPP and the OCM pathway (respectively), shows a significant increase in overweight/obese breast cancer patients compared to the lean patients." (PMID 34073320, 2021). "However, obesity (a variable linked to high cholesterol levels) is associated with a higher expression of G6PD and GART enzymes, as detected in the basal-like breast tumours of overweight/obese versus lean breast cancer patients." (PMID 34073320, 2021). "Silencing of G6PD MCF7 breast cancer cells reduced lipid synthesis and proliferation." (PMID 31302749, 2020). "Reduced G6PD activity has been found in doxorubicin-resistant breast cancer cells." (PMID 31500396, 2019). "G6PD has been previously reported to be important for tumor growth and for antioxidant defense, although the exact mechanism by which it is important in the proliferation of breast cancer cells is still unclear." (PMID 29290982, 2017). "Interestingly, exposure of breast cancer cell lines to hypoxia led to a repressed expression of G6PD, while increasing the expression of genes involved in serine synthesis pathway and mitochondrial folate cycle." (PMID 28649560, 2017). "Using this tool, we tested whether the mRNA expression of G6PD correlated with overall survival among patients with breast cancer and found that high G6PD mRNA expression correlated strongly with reduced overall survival (p = 0.00007)." (PMID 27078845, 2016). "G6PD independent supply of reducing quivalents is envisaged in canine mammary tumors." (PMID 28096627, 2016). "We next examined whether G6PD expression correlated with clinical outcomes in patients with breast cancer in publically available datasets and in a tissue microarray from patients with invasive breast cancer." (PMID 27078845, 2016). "Acrolein and phosphoramide mustard are the metabolites of cyclophosphamide that are among the causative agents, which reduce the activity of SOD, CAT, GPX, glutathione-S-transferase, and glucose-6-phosphate dehydrogenase in erythrocytes of CMF treated breast cancer patients." (PMID 26576218, 2015). "The G6PD protein expression was strongly associated with PFS of breast carcinoma patients (P = 0.021) but not for OS." (PMID 26607846, 2015). "In our analysis, G6PD was found to be up-regulated in cancer and bad prognosis in breast cancer." (PMID 24342878, 2013). "In breast carcinomas fra-1 Δct values (5.79–10.58) was lower because fra-1 mRNA could be detected at a number of cycles a little higher than that occurring for g6pd amplification." (PMID 17254320, 2007). "Furthermore, abnormal expression of G6PD has been detected in various cancer types, including ovarian cancer, leukemia, lung cancer, gastric carcinoma, hepatocellular carcinoma, pancreatic carcinoma, and breast cancer." (PMID 39796677, 2024). "The inhibition of G6PD could induce ERS and its associated autophagy deregulation in breast cancer." (PMID 38143739, 2023). "Furthermore, in this study, we showed that p52-ZER6 could enhance G6PD expression in estrogen receptor (ER)-positive breast cancer cells MCF-7." (PMID 36977688, 2023). "Additionally, the phosphorylation of the endogenous G6PD was significantly reduced by increasing the lactic acid levels in 3 independently tested (cervical HeLa, liver hepatocellular carcinoma cell HepG2 and breast cancer MCF-7) cell lines." (PMID 37491277, 2023). "G6PD inhibitors such as polydatin might be used to increase lapatinib effect on breast cancer." (PMID 30987650, 2019).
breast cancer (continued). "To verify these findings, we silenced PR expression in the luminal breast cancer cell lines, MCF7 and T47D, which led to accelerated proliferation and PPP activity with G6PD expression." (PMID 41423458, 2025). "PPP-related enzymes, including glucose 6-phosphate dehydrogenase (G6PD) and transketolase, have been revealed to be hyperactivated within breast cancer cells." (PMID 40809180, 2025). "The upregulation of NRF2 stimulates the expression of G6PD and activates HIF-1α, resulting in NOTCH1 signaling activation and breast cancer proliferation." (PMID 38424190, 2024). "NRF2 overexpression and KEAP1 knockdown promoted the expression of G6PD and HIF-1α/NOTCH1 to induce EMT and breast cancer migration." (PMID 38424190, 2024). "Nrf-2 activates antioxidant enzymes and upregulates Notch-1 through the G6PD/HIF-1 pathway, thereby affecting the proliferation of breast cancer cells." (PMID 35938165, 2022). "Previous studies have reported that high Nrf2 expression can enhance the expression of G6PD and HIF-1 in breast cancer cells." (PMID 35938165, 2022). "The modulation of glucose-6-phosphate dehydrogenase (G6PD)/ HIF-1α expression by Nrf2 is consequently involved in the Notch1 pathway-mediated regulation proliferation, migration, and invasion of breast cancer." (PMID 36289931, 2022). "In one study using leukemia cell lines, high level of G6PD was found in DOX-resistant cells 39, while in another study using low-metastatic human breast cancer, MCF-7 cell line, the level of G6PD was significantly decreased in DOX-resistant MCF-7 cells 40-42." (PMID 35173543, 2022). "Glucose-6-phosphate dehydrogenase (G6PD), the first and rate-limiting enzyme of the pentose phosphate pathway, is highly expressed in certain types of tumor, including lung cancer, breast carcinoma and RCC 7-9." (PMID 34975298, 2022). "The results indicated that EMC2, G6PD, FLT3, IFNG, ANO6, and SLC1A4 were positively correlated with ferroptosis while CISD1, TP63, and BRD4 were negatively correlated with ferroptosis in breast cancer." (PMID 34222241, 2021). "6-aminonicotinamide, a G6PD inhibitor, can decrease mammosphere formation and aldehyde dehydrogenase (ALDH) activity when given with DHEA in breast cancer stem-like cells that show high PPP activity." (PMID 34552932, 2021). "Examining clonogenic potential under metabolic stress, the dual pharmacological inhibition synergistically and dramatically suppressed the clonogenic potential of breast cancer cells; although clinically available, DHEA is an uncompetitive G6PD inhibitor." (PMID 32487689, 2020). "For example, the expression of glucose-6-phosphate dehydrogenase (G6PD) and 6-phosphogluconolactonase (6PGL) were elevated, implying a more activated PPP in HER2 subtype than other subtypes of breast cancer." (PMID 33489906, 2020). "Meanwhile, targeting G6PD induces apoptosis and enhances chemotherapeutic antitumor effects via ROS-mediated damage in certain cancer, including AML, lung cancer, breast cancer, and colorectal cancer." (PMID 33041664, 2020). "It has been suggested that the expression of G6PD and transketolase (TKT) are positively correlated to the decreased overall and relapse-free survival in breast cancer." (PMID 33489906, 2020). "Glucose-6-phosphate dehydrogenase (G6PD) is the key enzyme of the PPP, it is often over-expressed in several types of cancer such as breast cancer, oesophageal carcinoma, renal cancer and is correlated to worse prognosis." (PMID 30987650, 2019). "Nrf2‐dependent G6PD/HIF‐1α activation provokes Notch1 signalling by up‐regulation of Jagged1 and Hes1, thereby promoting EMT in breast cancer cells." (PMID 30809937, 2019).
breast cancer (continued). "As redox homeostasis plays an important role in breast cancer progression, we assessed the effect of TKT and G6PD silencing on ROS levels." (PMID 29290982, 2017). "Herein, we silenced the most important enzymes of this pathway — glucose-6-phosphate dehydrogenase (G6PD) and transketolase (TKT) — in the human breast cancer cell line MCF7." (PMID 29290982, 2017). "We surveyed three independent breast cancer gene expression datasets to explore the relation between TKT and G6PD expression and patient outcome." (PMID 29290982, 2017). "First, G6PD and TKT were silenced in the breast cancer cell line MCF7 and the impact on cell proliferation, survival and cell cycle was assessed." (PMID 29290982, 2017). "To understand the biological and metabolic role of these two enzymes in breast cancer, we separately silenced TKT (siTKT) and G6PD (siG6PD) in the breast cancer cell line MCF7 by using specific small interference RNAs (siRNA)." (PMID 29290982, 2017). "In addition, lactate enhances the pentose phosphate pathway by upregulating the activity of glucose-6-phosphate dehydrogenase (G6PD), thereby supporting redox homeostasis and promoting the proliferation of breast cancer cells." (PMID 41152975, 2025). "The results suggest that the combined treatment of pyrotinib and chrysin synergistically inhibits HER2-positive breast cancer cell survival and proliferation in vitro and in vivo by augmenting autophagy, which is accomplished through the miR-16-5p/ZBTB16/G6PD axis." (PMID 38110365, 2023). "The G6PD Y249/Y322 phosphorylation was drastically decreased or even absent in most tested human breast cancer samples." (PMID 37491277, 2023). "This hormone is produced by the brain, gonads, and adrenal glands and is one of the non-competitive inhibitors of the G6PD in breast cancer cells." (PMID 36992836, 2023). "17beta-estradiol (E2), 4-nonylphenol (NP), and BPA induce the G6PD activity in a concentration-dependent manner in the estrogen-sensitive human breast cancer cell (MCF-7 cells)." (PMID 36992836, 2023). "In breast cancer cells, GL-V9 promotes AMPK expression and activity, leading to a decrease in G6PD." (PMID 35663205, 2022). "Interestingly, RIP140 deficiency augments the stimulatory effect of estradiol on G6PD expression in MCF7 breast cancer cells, suggesting that RIP140 impairs estradiol-induced G6PD expression at least in ER+ breast cancer cells." (PMID 35806424, 2022). "Although the importance of 6PGD had till now been overshadowed by G6PD and TKT, recent evidence suggests that G6PD alone has only marginal effects on in vitro proliferation of some particular types of cancer cells, including breast cancer." (PMID 33498665, 2021). "Interestingly, our in vitro finding with exogenous cholesterol contradicts the data for the expression of G6PD and GART in the basal-like breast tumours of overweight/obese breast cancer patients." (PMID 34073320, 2021). "CB83, another G6PD inhibitor, can inhibit growth of MCF10-AT1 breast cancer cell line." (PMID 34552932, 2021). "Increased PPP flux by G6PD and HK2 enhancement induces tamoxifen resistance in breast cancer." (PMID 34552932, 2021). "Nrf2 overexpression can induce the activation of glucose-6-phosphate dehydrogenase (G6PD)/HIF-1α signaling, consequently conferring the proliferation and metastasis of breast cancer cells via EMT signaling (epithelial–mesenchymal transition) due to extensive NADPH levels." (PMID 33466626, 2021). "Modulation of glucose‐6‐phosphate dehydrogenase (G6PD)/ Hypoxia inducing factor 1α (HIF‐1α) expression by Nrf2 is therefore involved in the Notch1 pathway‐mediated regulation proliferation, migration, invasion of breast cancer." (PMID 30809937, 2019). "Finally, we have also shown that high expression levels of G6PD and TKT correlate with poor overall and relapse-free survival in several breast cancer patient datasets." (PMID 29290982, 2017).
breast cancer (continued). "Our data suggested G6PD, IDH1 and IDH2 may carry out a novel mechanism with adriamycin resistance in breast cancer." (PMID 25818003, 2015). "Our data suggest that the overexpression of Twist in breast cancer cells may result in EMR through up-regulating of PKM2, LDHA, and G6PD." (PMID 26342198, 2015). "The results failed to confirm DHEA's putative anti-tumor action on breast cancer through G6PD inhibition, as the enzyme blockade only becomes apparent at pharmacological concentrations of the steroid." (PMID 9052415, 1997). "In this study, we determined that pyrotinib combined with chrysin could elicit a synergistic superiority in inhibiting HER2-positive breast cancer in vitro and in vitro than single pyrotinib or chrysin treatment via the regulation of miR-16-5p/ZBTB16/G6PD axis." (PMID 38110365, 2023). "Importantly, positive correlations between immuno-enriched SRC protein and G6PD Y249/322 phosphorylation specifically manifest in ER/PR positive or HER negative types of breast cancer." (PMID 37491277, 2023). "Deciphering the molecular mechanism responsible for G6PD expression regulation, i.e., finding the transcription factor(s) mediating RIP140 effects in ER+ and ER− breast cancers, requires further investigations, and could improve our knowledge of transcriptional control of the PPP." (PMID 35806424, 2022). "Notably, G6PD, which is the rate limiting enzyme of the oxidative phase of PPP, has been shown to be aberrantly activated in HR+ breast cancer and contributes to tumor development and progression through decreased cellular autophagy, tumor relapse and drug resistance in breast cancer models." (PMID 34638293, 2021). "Immunohistochemical staining for PPP-related proteins (glucose-6-phosphate dehydrogenase [G6PDH], 6-phosphogluconolactonase [6PGL], 6-phosphogluconate dehydrogenase [6PGDH], and nuclear factor-erythroid 2-related factor 2 [NRF2]) was performed using tissue microarray (TMA) of 348 breast cancers." (PMID 29682102, 2018). "Therefore, the codelivery of G6PD inhibitors (such as RRx-001) and sonosensitizers in tumor tissues to deplete GSH and disrupt redox homeostasis may maximally enhance the treatment efficiency of SDT in breast cancer." (PMID 35601559, 2022). "Moreover, silencing of the G6PD did not prevent formation of K-Ras-induced non-small cell lung, or HCT116 colorectal, primary tumour growth in mice and only slightly decreased triple-negative MDA-MB-231 breast cancer formation." (PMID 34932167, 2021).
diabetes (75 papers, 2008 to 2026). "Baseline comorbidities such as diabetes mellitus, thyroid disorder, Helicobacter pylori infection, smoking status and chronic hepatitis are known to be associated with G6PD levels." (PMID 41374996, 2025). "G6PD deficient men have a higher risk of diabetes-related microvascular complications (odds ratio 1.37 [95% CI: 1.01, 1.86]), and are diagnosed with T2D, on average, 4.1 years later than non-carriers." (PMID 41022122, 2025). "Recent research studies have shown those harboring the G6PD p.Val68Met variant face potential diabetes undertreatment due to their lower HbA1c levels relative to blood glucose." (PMID 41362833, 2025). "The decrease in G6PD activity caused by diabetes-induced oxidative stress was investigated, and G6PD enzyme activity was restored using the powerful antioxidants SMe1EC2, timolol, and selenium." (PMID 39726786, 2024). "A recent publication highlighted an increase in RBC turnover commensurate with a decrease in HbA1c relative to glucose levels, and an increase in the incidence of diabetes complications (diabetic retinopathy) in individuals with a variant in the G6PD gene." (PMID 39530122, 2024). "Recently, it was demonstrated that individuals of African ancestry with a G6PD deficient risk allele presented an increased risk of diabetes complications, like retinopathy and neuropathy." (PMID 39519313, 2024). "Our study identified a significant elevation in the risk of type 2 diabetes mellitus (T2DM) among individuals carrying the G6PD rs72554664 variant, particularly the Kaiping variant denoted by the T allele, especially in hemizygous males." (PMID 38834682, 2024). "Clear examples such as African-enriched variants in APOL1 and G6PD have been shown to contribute to especially high risk of chronic kidney disease and to missed diabetes diagnosis, respectively." (PMID 36873096, 2023). "It was previously reported that reduced G6PD activity has been associated with several underlying diseases, such as diabetes and rheumatoid arthritis." (PMID 37967096, 2023). "An increased risk for diabetes, and also of diabetic complications such as proliferative retinopathy, has been reported in G6PD-deficient subjects." (PMID 36231003, 2022). "Several clinical disorders, such as diabetes and myocardial infarction, precipitate hemolysis in G6PD-deficient subjects." (PMID 36231003, 2022). "A high frequency of decreased G6PD activity, apparently unrelated to gene mutations, has been reported in ketosis-prone diabetes, an atypical form of diabetes common in male descendants of sub-Saharan Africans, primarily African American and African Caribbean." (PMID 36431166, 2022). "The severe insulin deficiency and metabolic decompensation in Ketosis-prone diabetes can alter G6PD activity." (PMID 35313968, 2022). "Among the potential outcomes related to G6PD loss of function, birth defects, heart disease, diabetes, and neurodegeneration are highlighted." (PMID 36231003, 2022). "In diabetes, there is as association between increased activity of G6PD and endothelial and vascular dysfunction and elevated levels of NADPH." (PMID 35805067, 2022). "In line with the findings of this meta-analysis, increased fasting glucose levels and diabetes were detected among G6PD-deficient subjects from Singapore, the western Amazon, and Saudi Arabia." (PMID 34007401, 2021). "In fact, the overexpression of G-6-PD decreases endothelial cell oxidative stress and the risk of diabetes, β-cell apoptosis and insulin resistance are increased with deficiency or decrease of G6PD." (PMID 33778463, 2021). "Knockdown of G6PD and treatment with high glucose mimicked the phenotype of G6PD deficiency and diabetes, with more detrimental effects in combination compared to either condition alone." (PMID 33050491, 2020). "G6PD status is associated with many human diseases, including hemolytic disorders, cardiovascular diseases, and diabetes." (PMID 30661088, 2019).